EGFR (epidermal growth factor receptor)
Diseases named in the same sentence as EGFR in open-access papers (continued):
Sharing a sentence is not in itself a finding about the gene and the disease.
cancer (continued). "EGFR aberrations activate multiple downstream pro-oncogenic signaling pathways and subsequently induce biological processes that are beneficial to cancer maintenance and progression, including chronic initiation, metabolic regulation, and cell-cycle regulation." (PMID 30404194, 2018). "Thus, the polyclonality of C797S, together with co-existing resistance mechanisms, highlight the heterogeneity of resistant EGFR-mutant cancers." (PMID 29455654, 2018). "Thus, EGFR α2-6-sialylation is consistently correlated with increased tyrosine kinase activity despite the diverse genetic lesions present in the 3 distinct cancer lines." (PMID 29402301, 2018). "In one study, the authors found that by targeting particular oncogenes such as HER-2, BCR-ABL, and EGFR, they were able to cause cancer cells to revert to a noncancerous phenotype and arrest tumor growth." (PMID 30518036, 2018). "We hypothesized that this complex inhibitor can negatively affect the survival of cancer cells by suppressing the downstream signaling of EGFR." (PMID 29515106, 2018). "Additionally, in a study on laryngeal SCC, a cancer which is strongly correlated with tobacco exposure, mTOR and EGFR pathways were highly overexpressed." (PMID 30308005, 2018). "However, capture efficiency was reduced by low levels of EGFR expression, and the CTC-chip is likely insufficient to capture cancer cells with much lower EGFR expression." (PMID 30104638, 2018). "Since EGFR is an important molecule for targeting cancer therapy, simultaneous blockade of TEM8 and EGFR may potentially have more potent anti-cancer effects." (PMID 30241478, 2018). "Our studies are the first to examine the intersection of p120ctn down-regulation and EGFR overexpression, though we hypothesize that these genetic alterations most likely traverse in many cancer types in addition to ESCC." (PMID 29541406, 2018). "Additionally, the effect of ST6Gal-I on cancer cells treated with the common EGFR inhibitor, gefitinib, was evaluated." (PMID 29402301, 2018). "It is anticipated that the findings reported here may provide very useful information for designing effective drugs for the treatment of EGFR-related cancer disease." (PMID 30563058, 2018). "Therefore, we treated cancer cell lines expressing different MDR conferring genes (P-glycoprotein, BCRP, ABCB5 and mutation-activated EGFR) with BetA." (PMID 29867487, 2018). "We have provided evidence that CD133 expression is positively associated with EGFR-TKI resistance and high levels of EHD1 in patients, and NF-κB/miR-590/EHD1 acts as a novel mechanism, promoting EGFR-TKI resistance via enhanced cancer CSC-like properties in vitro and in vivo." (PMID 29549343, 2018). "Silibinin shows anti-cancer effect on EGFR TKI resistant cell NCI-H1975, which indicating silibinin may overcome the resistant to first generation TKIs (gefitinib and erlotinib)." (PMID 29472856, 2018). "Through the inhibition of ATP binding to EGFR, the EGFR TKIs block auto-phosphorylation and the activation of downstream signaling pathways, leading to the inhibition of cell proliferation and the induction of apoptosis in cancer cells." (PMID 29371589, 2018). "In cancer cells, the stability of EGFR is promoted by the chaperon protein HSP90." (PMID 29777377, 2018). "Aberrant EGFR signaling is involved in poor prognosis of many types of cancer." (PMID 30497501, 2018). "The EMT was reported to play a critical role in cancer metastasis and EGFR-TKI resistance." (PMID 29548337, 2018). "Our studies demonstrated that high glucose in vitro might be regarded as an accelerator to increase cancer cell proliferation by enhancing the glial cell line-derived neurotrophic factor (GDNF)/RET or epidermal growth factor (EGF)/EGFR signaling pathways." (PMID 30455857, 2018). "We found that EGFR levels were increased in the SphK1-overexpressing cancer cells." (PMID 29385066, 2018).
cancer (continued). "Thus, STAT3 is capable of exacerbating β-catenin and inducing PDGFA to promote Wnt signaling for maintaining the formation and survival of cancer stem-like tumorspheres in selective EGFR-positive CRCs." (PMID 30068339, 2018). "Specifically, we assessed whether the disruption of nuclear import of EGFR affected cancer cell proliferation." (PMID 29599917, 2018). "The EGFR expression level varies widely in different types of cancer cells." (PMID 30510514, 2018). "Notch1-dependent regulation of EGFR has been described in several types of cancers." (PMID 29321718, 2018). "Hence, dissecting the EGFR 23 or Met 24 pathways activated by ligand binding is relevant to cancer therapeutics." (PMID 29575431, 2018). "Thus, detection of EGFR expression level in malignant tumors can provide important prognostic and predictive information that can influence the stratification of cancer treatment for patients." (PMID 30231504, 2018). "Finally, it is important to stress that besides oncogenic alterations, inappropriate activation of the EGFR in cancer can originate from derailed receptor endocytosis and trafficking." (PMID 29124875, 2018). "Therefore, luteolin molecule playsan important role in inhibiting mutant EGFR and thus should beimplicated as a potential agent in cancer therapy." (PMID 30108422, 2018). "In addition, the FDA-approved TKI of afatinib for EGFR targeting also illustrates great anticancer activity on cancer cell death occurrence, cell growth inhibition, and cell cycle arrest in SW579 cells, an EGFR expressing human ATC cell line." (PMID 29849821, 2018). "The epidermal growth factor receptor ErbB signalling network was analysed by integrating high-level details into a mass-action-based modelling framework and therapeutic antibodies to target the cancer-related ErbB3 RTK were developed." (PMID 29699481, 2018). "Single-chain variable fragment (scFv) of antibodies may have high affinity to antigens (e.g. EGFR) overexpressed in cancer cells and have been used to engineer oHSV envelope glycoproteins to target tumor." (PMID 30799657, 2018). "EGFR activation promotes cancer cell division, survival, metastasis, and cellular repair." (PMID 29784046, 2018). "In addition, ERBB4 is the least expressed EGFR member in all cancer cell lines, even though some studies have implied that ERBB4 plays an important role in cancer development." (PMID 29849821, 2018). "In conclusion, NIR-PIT with can225-IR700 is a promising treatment for canine EGFR-expressing cancers, including invasive transitional cell carcinoma in pet dogs, that could provide a pathway to translation to humans." (PMID 29721181, 2018). "Moreover, it is a proto-oncogene, with homology to the EGFR sequence and its overexpression has been observed in multiple types of cancer and used in treatment measures against cancer." (PMID 30138436, 2018). "Recent work by our lab demonstrated a critical role for EGFR signaling in ALK+ cancer cells." (PMID 29507657, 2018). "Meanwhile, as an EGFR inhibitor, it is also interesting to investigate whether the combination of silibinin and other EGFR inhibitor (gefitinib and erlotinib) could overcome the drug resistance in cancer therapy." (PMID 29472856, 2018). "Furthermore, a positive clinical outcome is reported for a cancer patient treated with the combination of an anti-EGFR mAb and anti-NGcGM3 therapy." (PMID 29844873, 2018). "Our results advanced these reports by demonstrating that honokiol may exert these auxiliary anti-cancer roles via an EGFR-mediated JAK-STAT3 signaling pathway." (PMID 30587839, 2018). "Phospholipase C, gamma 1 (PLCG1) is most notably characterized in cancer by activation of cellular proliferation in response to growth factors such as epidermal growth factor receptor (EGFR) and platelet derived growth factor receptor (PDGFR), both common pathways altered in GBM." (PMID 29946469, 2018).
cancer (continued). "Examples in many human cancers include copy number loss of the gene that codes for the tumor suppressor protein PTEN and copy number gain in the gene that codes for the proto-oncogene EGFR." (PMID 29342193, 2018). "The distribution of differentially located EGFR proteins in cancer tissues had shown 36 (22.36%) with high mEGFR and nEGFR staining, 33 (20.50%) with high mEGFR and low nEGFR staining, 27 (16.77%) with low mEGFR and high nEGFR staining, and 65 (40.37%) with low mEGFR and nEGFR staining." (PMID 29950164, 2018). "Epidermal growth factor receptor (EGFR), anaplastic lymphoma kinase (ALK), v-raf murine sarcoma viral oncogene homolog B1 (BRAF), and c-ros oncogene 1 (ROS1) mutations are now used to guide specific anti-cancer therapies to improve patient outcomes." (PMID 30065223, 2018). "However, claims data do not contain clinical information that is relevant to eligibility for EGFR testing, such as the date of diagnosis, cancer stage, histological subtype of disease, and tissue availability." (PMID 29554880, 2018). "Therefore, it is possible that the TGFα-EGFR signaling axis promotes cancer cell proliferation, invasion, and metastasis, all of which drive the aggressiveness of TNBC and lead to poor response to EGFR inhibitors." (PMID 30034618, 2018). "According to Igal and co-workers, SCD1 may control cancer cell proliferation via modulation of the epidermal growth factor (EGFR → Akt/ER) signaling pathway." (PMID 29396722, 2018). "Anti-EGFR immunoliposomes containing celecoxib for the treatment of cancer were prepared." (PMID 29315231, 2018). "Interestingly, a large body of evidence indicates that the Notch pathway is intimately coupled to EGFR or its downstream targets, both in development and in cancer." (PMID 29857516, 2018). "This driving role in malignancy has made EGFR a key target for anti-cancer therapy." (PMID 30337523, 2018). "The activation of EGFR can trigger a series of downstream signaling pathways, principally the mitogen-activated protein kinase (MAPK) and PI3 K/AKT pathways that are associated with proliferation, invasion and metastasis of cancer cells." (PMID 30479571, 2018). "HER-2 and EGFR are biological targets related to the development of cancer and the discovery and/or development of a dual inhibitor could be a good strategy to design an effective drug candidate." (PMID 30477154, 2018). "Therefore, multimodality drugs concurrently aiming at several targets in the circuit of putative feedback mechanism of EGFR and drug resistance-related enzymes would probably provide more benefits for cancer patients." (PMID 29855336, 2018). "It is believed that this fusion protein can substitute EGFR signaling and may act to promote inflammation in the cancer site as well." (PMID 29933636, 2018). "Amplification of many RTKs occurs in a variety of human cancers, such as EGFR, ERBB2 and MET." (PMID 29455648, 2018). "As our erlotinib-treated PIK3CA-comutated case, these data suggest that PIK3CA-mutations despite being considered cancer-drivers do not necessarily represent a mechanism of primary resistance to erlotinib in EGFR-mutated NSCLC." (PMID 29899852, 2018). "The epidermal growth factor receptor (EGFR) pathway substrate 8 gene (Eps8) is involved in regulating cancer progression and might be an ideal antigen." (PMID 29515106, 2018). "Several Anti-EGFR mAbs are register for the treatment of human cancer." (PMID 29844873, 2018). "This newly identified AMPK/Skp2/Akt pathway provides not only the molecular basis of how AMPK serves a protective and survival advantage under diverse stresses, but also offers a novel therapeutic strategy for cancer treatment and overcoming acquired resistance to EGFR targeted therapy." (PMID 30413706, 2018). "This has led to an emerging concept that concomitant targeting of EGFR and stress pathways might offer a window of opportunity in cancer treatment." (PMID 29124875, 2018).
cancer (continued). "Yet, ERBB1 (EGFR) mutations are not likely to contribute to responses in most human cancers besides demonstrated efficacies in NSCLC." (PMID 29933636, 2018). "Indeed, EGFR tyrosine kinase inhibitors, which suppress cancer cell proliferation and induce apoptosis, cell cycle arrest, and senescence, are now standard therapy for advanced cases with activating EGFR mutations." (PMID 29784046, 2018). "EGFR has been proved to be one of target genes of miR-133b in several human cancer cells." (PMID 30479571, 2018). "That receptor is found in many types of cancer similar to EGFR." (PMID 29098884, 2018). "To test the hypothesis that the S100A9+ MDSC-derived macrophages can protect cancer cells from EGFR-TKI killing, we isolated CD14+ monocytes from PBMCs and induce them into macrophages (monocytes-derived macrophages, MDMs)." (PMID 29484139, 2018). "The benefits of EGFR TKIs observed with EGFR mutation-positive cancers does not translate to patients who have high EGFR expression identified using immunohistochemistry or increased EGFR copy number detected by fluorescence in situ hybridization." (PMID 30065223, 2018). "We test the half-life of EGFR with CHX in both WT and HCRP knockdown cancer cells to clarify whether EGFR stability contributed to the activated EGFR–AKT pathway in HCRP knockdown cells." (PMID 30518879, 2018). "Activation of Axl in RTK-resistant cancer such as EGFR may occur due to bypassing of the RTK inhibitor effect." (PMID 30322068, 2018). "Answers to this question may reveal the core mechanism(s) underlying the KID pro-survival function of EGFR and should reveal new targets for the treatment of EGFR-dependent cancers." (PMID 29358623, 2018). "Moreover, in cancer models, there is evidence of bidirectional cross-talk between sex steroid receptors, including androgen and progesterone receptors, and EGFR signaling pathways." (PMID 30012205, 2018). "In cancer cells, constitutive activation of the EGFR is common due to EGFR overexpression." (PMID 30400136, 2018). "Some communities derived from specific cancer pathways, such as the community containing EGFR, which simultaneously captured signaling from related ErbB proteins and the role of cell adhesion and tissue migration in EGFR‐dependent transformation." (PMID 30573688, 2018). "EGFR is a well-known oncogene and an effective rational target of anti-cancer therapies." (PMID 30449278, 2018). "The KID functions of EGFR offer a new window for targeting EGFR expressing cancers." (PMID 29358623, 2018). "Furthermore, these effects were linked to the activation of the EGF receptor as attenuation of EGFR resulted in a substantial reduction of the cancer cell growth-inhibitory effect." (PMID 30514247, 2018). "The EGFR is one of the most plausible treatment targets in this cancer entity." (PMID 30129426, 2018). "Altogether, this study revealed that LOX expression is regulated by the EGFR pathway and this may account for the anti-cancer metastasis effects of silibinin, indicating LOX as a potentially therapeutic target for NSCLC treatment." (PMID 29472856, 2018). "EGFR is a receptor tyrosine kinase known to be involved in multiple cancers." (PMID 29987260, 2018). "The presence of SP-D in these cancers could exert a protective effect via downregulation of the EGFR pathway." (PMID 30127783, 2018). "ANKRD1 might be closely correlated with the drug-tolerant subpopulation of cancer cells which is commonly involved in the drug resistance to EGFR-TKIs." (PMID 30291293, 2018). "It is therefore possible that the mechanism of resistance to afatinib differs from that of 1st generation EGFR-TKIs, and it might lead to higher anti-cancer efficiency with osimertinib treatment." (PMID 30550608, 2018). "In order to analyze whether the increased avidity of the α-EGFR-EGFR TM influences its ability to redirect UniCAR-engrafted T cells for an efficient killing of different EGFR+ cancer cells, chromium-based killing assays were performed." (PMID 29876011, 2018).
cancer (continued). "Furthermore, EVs released by human BC cell lines containing the epidermal growth factor receptor (EGFR) ligand amphiregulin increase invasiveness of recipient cancer cells." (PMID 29632535, 2018). "Several cancer signaling pathways involving PKA, AMP-activated protein kinase (AMPK) and epidermal growth factor receptor-retrovirus associated sequence oncogene signaling pathway (EGFR-RAS) activate DRP1 driven mitochondrial fission, as will be discussed later." (PMID 29466320, 2018). "Overall, EGFR expression was detected in the large majority of cancers (64/74, 86.5%)." (PMID 29700411, 2018). "The epidermal growth factor receptor (EGFR) is oncogenic receptor tyrosine kinase that is often overexpressed/overactivated in cancers of epithelial origin, and drugs targeting the tyrosine kinase activity of EGFR have been developed as putative therapeutics to treat such malignancies." (PMID 29358623, 2018). "Thus, PGRMC1 contributes to cancer proliferation and chemoresistance through interaction with EGFR or cytochrome P450 by forming a unique heme-stacking dimer structure in response to heme concentration in cancer cells." (PMID 30087538, 2018). "LAPTM4B is up-regulated in many human cancer cells and has been suggested to be involved in recruitment of the leucine transporter to lysosomes, regulation of epidermal growth factor receptor lysosomal sorting and degradation, and facilitating Cer removal from late endosomes." (PMID 30481169, 2018). "EGFR continues to be an attractive target for the design and development of compounds that can specifically bind to it and inhibit its tyrosine kinase (TK) activity and its signal transduction pathway in cancer cells." (PMID 30274538, 2018). "In addition, epidermal growth factor receptor, EGFR-enriched EVs produced by cancer cells are uptaken by endothelial cells, inducing vascular endothelial growth factor (VEGF) and VEGF receptor 2 expression, while TF-containing EVs upregulate angiogenesis." (PMID 29158316, 2018). "This phenomenon may be attributed to the cross talk between TGF‐β signaling and other pathways, including EGF receptor (EGFR) signaling during cancer progression." (PMID 29215776, 2018). "Previous studies demonstrated that miR-133b could restrain cell invasion and metastasis via targeting EGFR in a variety of cancer cells, including ovarian cancer, non-small-cell lung cancer, and colorectal cancer." (PMID 30479571, 2018). "Taken together, our data suggest that MHYs act as irreversible EGFR inhibitors and their anti-cancer effects including activation of Src and induction of apoptosis may require prior inhibition of EGFR." (PMID 30158525, 2018). "A mono-biotinylated nanobody could be used to direct various therapeutic agents to EGFR overexpressing cancer cells." (PMID 30348204, 2018). "Given its critical role in cancer, several EGFR‐targeted therapies have been developed, including monoclonal humanized antibodies (mAbs) directed against the receptor extracellular domain, as well selective small‐molecule inhibitors targeting the tyrosine kinase domain." (PMID 29124875, 2018). "While no preclinical models have been reported to exhibit this behavior, it seems likely that this will be driven by marked transcriptional reprogramming similar to induction of EMT where switching to the SCLC lineage would relieve cancer cells of their dependence on mutant EGFR." (PMID 29458371, 2018). "The clinical trials of three unique peptides of EGFR as NSCLC cancer vaccines are under way." (PMID 30400835, 2018). "However, the significance of the interaction of endogenous WT RAS proteins with p110α has not previously been addressed in the context of oncogenic EGFR signaling and in EGFR-mutant-driven cancer models." (PMID 30590030, 2018). "Three unique peptides of EGFR may be used as cancer vaccines in the treatment of patients with NSCLC." (PMID 30400835, 2018).